IRAK3 (interleukin 1 receptor associated kinase 3)
Diseases named in the same sentence as IRAK3 in open-access papers (continued):
Sharing a sentence is not in itself a finding about the gene and the disease.
asthma (21 papers, 2009 to 2026). "IRAK3 dysregulation is also associated with accelerated and exacerbated asthma and infectious diseases, and increased IRAK3 expression in peripheral blood leucocytes is associated with reduced disease activity in RA." (PMID 40370470, 2025). "IRAK-M has several anti-inflammatory activities, and single nucleotide polymorphisms in the IRAK3 gene were associated with higher susceptibility to asthma, likely due deficient anti-inflammatory responses in airway epithelial cells." (PMID 36865541, 2023). "We further identify a conserved C-lobe surface on IRAK3 that harbors asthma-associated mutations and closely resembles the previously reported IRAK4 homodimer interface." (PMID 33238146, 2021). "Strikingly, both residues of the asthma-associated mutations in IRAK3 lie within or are directly adjacent to this conserved surface." (PMID 33238146, 2021). "Conversely, the IRAK3 hub-high traffic gene is an important inflammatory mediator associated with asthma susceptibility and SARS-CoV-2 increases risk of asthma in COVID-19 patients by increasing expression of this gene." (PMID 34975885, 2021). "IRAK3 is thought to be a negative regulator of innate immune signaling and mutations in IRAK3 are associated with asthma and cancer." (PMID 33238146, 2021). "Combining these findings with the results of differential expression analysis, network analysis, and differential metabolites, we identified several key pathogenic pathways for asthma (including IRAK3 and ADRB2) that can be altered by the viral infection." (PMID 33156843, 2020). "On the other hand, IRAK3 has recently emerged as a susceptibility candidate gene for asthma." (PMID 36611613, 2022). "Asthma-associated mutations and structural analyses suggest new mechanistic models on how IRAK3 might function as a negative regulator of innate immunity." (PMID 33238146, 2021). "First, SARS-CoV-2 infection might alter the expression of several key inflammatory genes: IRAK3, which is associated with asthma; ADRB2, which is an essential genetic factor for asthma; and NFKBIA, which shows critical transcriptional responses in childhood asthma." (PMID 33156843, 2020). "By conducting bioinformatics analysis, we identified five genes (CEBPE, HDC, IRAK3, PRR4, and SOD2) associated with asthma." (PMID 41602038, 2026). "After adjusting for confounding factors such as gender and age, these five genes (CEBPE, HDC, IRAK3, PRR4, and SOD2) were still independent risk factors for asthma." (PMID 41602038, 2026). "Significantly greater expression of IRAK3 was found in healthy individuals, patients with chronic persistent asthma, and patients with acute exacerbation of asthma." (PMID 41602038, 2026). "For the path where PM2.5 affects asthma through IRAK3, the indirect effect was 0.011 [95% CI (0.028, 0.085), p = 0.46], with an SE of 0.014 and a z/t value of 0.739." (PMID 41602038, 2026). "IRAK-M, encoded by IRAK3, regulates the toll-like receptor/interleukin-1 receptor pathway and NF-κB pathway, and IRAK3 was identified as an asthma susceptibility gene." (PMID 33156843, 2020). "Integrative analyses of metabolomics and transcriptomics (bulk and single-cell) data from asthma patients indicate that COVID-19 shares an intermediate inflammatory molecular profile with asthma (including IRAK3 and ADRB2)." (PMID 33156843, 2020). "Utilizing 2 bulk RNA-Seq datasets (GSE63142 and GSE130499) of asthma patients compared to healthy controls, we identified that IRAK3 and ADRB2 had significantly elevated expression (false discovery rate [FDR] < 0.05) in asthma patients." (PMID 33156843, 2020). "IRAK3 and ADRB2 are among the 6 overlapped genes, potentially implicating the roles of IRAK3 and ADRB2 in COVID-19-associated asthma at the single-cell level as well." (PMID 33156843, 2020). "Notably, IRAK3 is highly expressed in severe asthma and COVID-19 cohorts, where levels of L-citrulline and L-arginine are decreased in sera of COVID-19 and asthma patients." (PMID 35269704, 2022).
asthma (continued). "For instance, in addition to the IRAK3 hub-high traffic gene (described in the lightgreen module section), increased ADRB2 hub-high traffic gene expression during SARS-CoV-2 infection also increased the risk of asthma in COVID-19 patients." (PMID 34975885, 2021). "SARS-CoV-2 increased the expression of IRAK3 and ADRB2, which lead to a higher risk of asthma." (PMID 33156843, 2020). "In addition, IRAK3 rs1821777, which showed a nominal signal in the present study, has also been reported to be related to asthma in North Americans (P = 0.03) and in Sardinians (P = 0.001) of Italy." (PMID 23967269, 2013). "By analyzing asthma-associated mutations, we identify an evolutionarily conserved surface on IRAK3 that could form an interaction interface with IRAK4, suggesting a model for the negative regulation of IRAK4 by IRAK3." (PMID 33238146, 2021). "In this study, a mediation effect analysis was conducted to elucidate the potential mediating mechanisms between PM2.5 and the onset of asthma, involving several potential mediators, including CEBPE, HDC, IRAK3, PRR4, and SOD2." (PMID 41602038, 2026). "This study provided evidence that CEBPE, HDC, IRAK3, PRR4, and SOD2 mediate the connection between PM2.5 and the onset of asthma." (PMID 41602038, 2026). "The results revealed that five genes of interest (CEBPE, HDC, IRAK3, PRR4, and SOD2) showed a strong mediating effect between PM2.5 and the onset of asthma, suggesting that PM2.5 may alter the expression of these genes, thereby causing the onset of asthma." (PMID 41602038, 2026). "To determine the role of these key genes in the occurrence of asthma caused by environmental pollution, we provided strong evidence that the expression of genes of interest (CEBPE, HDC, IRAK3, PRR4, and SOD2) increased significantly in 160 participants with asthma." (PMID 41602038, 2026). "Altogether, altered IRAK3 and ADRB2 expression may explain relationships between COVID-19 and asthma, though these findings require experimental and clinical validation in patients with these disorders." (PMID 33156843, 2020). "Finally, five genes (CEBPE, HDC, IRAK3, PRR4, and SOD2) were identified as overlapping features across all three algorithms, as illustrated in the Venn diagram, and were thus considered robust candidate biomarkers for asthma." (PMID 41602038, 2026). "Although no drug for IRAK3 is used in the clinic, this analysis suggests it may serve as a relevant drug target for asthma and other related diseases." (PMID 36823319, 2023).
COVID-19 (8 papers, 2020 to 2024). A disease caused by infection with severe acute respiratory syndrome coronavirus 2. "Also, while IRAK2 was elevated in monocytes from patients with moderate or severe COVID-19, IRAK3 was only increased in severe COVID-19." (PMID 37310504, 2023).
diabetes (8 papers, 2013 to 2024). "Although age, gender, cigarette smoking, and alcohol drinking were matched between patients and controls, other variables, such as hypertension, diabetes mellitus, and chronic renal disease, may be confounding factors that may affect serum IRAK3 levels." (PMID 39346771, 2024). "IRAK3, a key inhibitor of inflammation, promotes diabetes development." (PMID 34872451, 2021). "A previous study found that IRAK3 expression in liver tissue was related to diabetes development." (PMID 34872451, 2021). "By analyzing the protein-protein interaction (PPI) and coexpression networks of the transcriptomes of different groups, it is inferred that Lrrk2 and Irak3 may be pharmacodynamic genes for type 2 diabetes mellitus (T2DM)." (PMID 32351607, 2020).
metabolic syndrome (7 papers, 2012 to 2025). A cluster of metabolic risk factors for CARDIOVASCULAR DISEASES and TYPE 2 DIABETES MELLITUS. "Recently, we showed that decreased expression of IRAK3 in monocytes of obese patients is associated with a high prevalence of metabolic syndrome; weight loss results in an increase in IRAK3 that is associated with decreased systemic inflammation." (PMID 23620818, 2013). "We identified the TLR2 signaling pathway as most deregulated canonical pathway with IRAK3 as downregulated key inhibitor that is associated with obesity-associated metabolic syndrome and loss of protective action of adiponectin against cardiovascular disease." (PMID 22272346, 2012). "Furthermore, interleukin-1 receptor-associated kinase 3 (Irak3), a cytokine signaling modulator that play an important role in obesity and metabolic syndromes by regulating inflammatory responses, is upregulated with age." (PMID 37943864, 2023). "IRAK3 is a key inhibitor of inflammation in association with obesity and metabolic syndrome." (PMID 22272346, 2012). "Weight loss was associated with an increase in IRAK3 and a decrease in SOD2, in association with a lowering of systemic inflammation and a decreasing number of metabolic syndrome components." (PMID 22272346, 2012). "Low IRAK3 and high SOD2 was associated with a high prevalence of metabolic syndrome (odds ratio: 9.3; sensitivity: 91%; specificity: 77%)." (PMID 22272346, 2012). "Irak3 is a crucial inhibitor of inflammation, obesity, and metabolic syndrome." (PMID 32351607, 2020). "Here, we identified IRAK3 as a key inhibitor of TLR2/NFκB-mediated chronic inflammation that is negatively associated with oxidative stress, and obesity-related insulin resistance and metabolic syndrome." (PMID 22272346, 2012). "Receiver operating characteristic curve analysis revealed that IRAK3 (mean AUC, 95%CI: 0.63, 0.54–0.72, P<0.05), TNFAIP3 (0.65, 0.56–0.73, P<0.01), SOD2 (0.69, 0.60–0.77, P<0.001), and TNFα (0.71, 0.62–0.78, P<0.001) were associated with metabolic syndrome." (PMID 22272346, 2012). "Low IRAK3 in combination with high SOD2 expression is a marker of the metabolic syndrome." (PMID 22272346, 2012). "Interestingly, the combination of low IRAK3 and high SOD2, a marker of mitochondrial oxidative stress was the strongest predictor of metabolic syndrome; it was even stronger than hs-CRP, the most widely used marker of systemic inflammation that was shown to be associated with metabolic syndrome." (PMID 22272346, 2012).
Obesity (7 papers, 2012 to 2023). Accumulation of substantial excess body fat. "We further identified the mechanistic link between obesity and IRAK3 depletion in circulating monocytes by exposing human monocytic culture cells to variable concentrations of the obesity-associated hormone adiponectin." (PMID 22272346, 2012). "Our lab has previously shown that obesity-associated low levels of globular adiponectin decreases the expression of interleukin-1 receptor-associated kinase-3 (IRAK3) in monocytes." (PMID 22393448, 2012). "We identified the increase in reactive oxygen species in combination with obesity-associated low adiponectin and high glucose and interleukin-6 as cause of the decrease in IRAK3 in THP-1 cells in vitro." (PMID 22272346, 2012). "We showed that IRAK3 in monocytes is downregulated in obesity before the development of T2DM and cardiovascular disease and that its expression increased with weight loss." (PMID 22272346, 2012). "To identify the mechanistic link between obesity and IRAK3 depletion in circulating monocytes, we investigated the effect of high (as in lean controls) and low (as in obese persons) levels of adiponectin on IRAK3 expression." (PMID 22272346, 2012). "In summary, we have demonstrated a bidirectional relation between adiponectin and IRAK3 in obesity." (PMID 22272346, 2012). "Surprisingly, we did not detect any major effect of injury and obesity on the expression levels of TNF or the associated genes Bcl3, Errfi1, Irak3, Myd88, and Thbs1 in our obese model." (PMID 29922174, 2018).
lung carcinoma (6 papers, 2017 to 2025). "Murine breast cancer cell line EO771 and lung cancer cell line LLC1 showed significantly delayed growth in IRAK3-KO mice, leading to prolonged survival of the LLC1 tumor–bearing mice." (PMID 36757800, 2023). "A small number of studies showed that tumor cell-intrinsic IRAK3 could also support the progression of tumor cells in colorectal and lung cancers." (PMID 33658057, 2021).
atherosclerosis (5 papers, 2013 to 2024). A disease characterized by the build-up of fatty material and calcium deposition in the arterial wall resulting in partial or complete occlusion of the arterial lumen. "In aggregate, our results emphasize an interaction between PPAR agonist-mediated increase in adiponectin and macrophage-associated Irak3 in the protection against atherosclerosis by PPAR agonists." (PMID 23620818, 2013). "Furthermore, aortic extracts of high-fat insulin-resistant LDL-receptor deficient mice, with lower adiponectin and Irak3 and higher Mcp1, showed accelerated atherosclerosis." (PMID 23620818, 2013). "Through analysis of the public database, seven hub genes (UQCR11, UBE2N, ADD1, TLN1, IRAK3, LY96, and MAP3K1) have recently been found to be strongly associated with familial hypercholesterolemia and contribute to a higher risk of atherosclerosis." (PMID 34895070, 2021). "Our study identified seven core genes (UQCR11, UBE2N, ADD1, TLN1, IRAK3, LY96, and MAP3K1) that are strongly linked to FH and lead to a higher risk of atherosclerosis." (PMID 32760426, 2020). "Because defective leptin signaling was found to modulate inflammation and atherosclerosis, we also studied the relation between low adiponectin (Adipoq) and Irak3 expression in aortic extracts of high-fat and insulin resistant LDL-receptor deficient mice characterized by high plasma leptin levels." (PMID 23620818, 2013).
colitis (5 papers, 2013 to 2025). Inflammation of the colon. "In mouse models of DSS-induced colitis, deletion of IRAK3 significantly lowers serum IL-1β levels and reduces intestinal inflammation." (PMID 40979590, 2025). "On the other hand, IRAK3 knockout mice stimulated using colitis-induced model show significantly increased mRNA and protein expression of TNF-α and IL-6 compared to IRAK3 wild type mice." (PMID 35167625, 2022).
colon cancer (5 papers, 2013 to 2024). "These dynamics are similar to those for colon cancer cells where IRAK3 is silenced in association with promoter-region DNA hypermethylation and when reactivated by induced demethylation, is associated with SURVIVIN down-regulation." (PMID 24162015, 2013).
influenza (5 papers, 2011 to 2018). An acute viral infection of the respiratory tract, occurring in isolated cases, in epidemics, or in pandemics; it is caused by serologically different strains of viruses (influenzaviruses) designated A, B, and C, has a 3-day incubation period, and usually lasts for 3 to 10 days. "Mice lacking IRAK3 have an increased mortality rate compared to wild type in influenza-induced pneumonia." (PMID 27403523, 2016).
ischemic stroke (5 papers, 2018 to 2025). A stroke disorder caused by obstruction of blood flow to the brain, due to thrombotic (local blood clot formation) or embolic (due to a blood clot or other material traveling from another site) event. "IRAK3 may have a great impact on NK cell during coronary occlusion and ischemic stroke." (PMID 40922361, 2025). "Interestingly, APAF1 and IRAK3 expression correlated negatively with NK cell abundance in both acute myocardial infarction and ischemic stroke, whereas ATM, CAPN1, IL1B, IL1R1, PRKACA, PRKACB, and TNFRSF1A correlated negatively with NK cell abundance in acute myocardial infarction." (PMID 35432334, 2022). "Interestingly, in acute MI and ischemic stroke, the expression of APAF1 and IRAK3 was negatively correlated with the abundance of NK cells, while the expression of ATM, CAPN1, IL1B, IL1R1, PRKACA, PRKACB and TNFRSF1A was positively correlated with the abundance of NK cells in MI." (PMID 38526027, 2024).
melanoma (5 papers, 2010 to 2024). A malignant, usually aggressive tumor composed of atypical, neoplastic melanocytes. "IRAK3- and Wnt10b-related genes are the major pathways associated with recurrent melanoma in younger and older patients with tumor-positive SLNs, respectively." (PMID 33373316, 2020). "In patients with melanoma treated with a CTLA4 blocking antibody, IRAK3 mRNA in the blood is included in a 4-gene panel to predict patient outcome." (PMID 36757800, 2023). "Depletion of myeloid cells reverted the tumor growth delay in Ret melanoma-bearing IRAK3-KO mice but had no impact in the WT counterparts." (PMID 36757800, 2023).
pneumonia (5 papers, 2012 to 2016). An acute, acute and chronic, or chronic inflammation focally or diffusely affecting the lung parenchyma, caused by an infection in one or both of the lungs (by bacteria, viruses, fungi, or mycoplasma.). "Furthermore, IRAK3 is cleaved in alveolar macrophages during pneumonia and is an important regulator by which tumor-associated macrophages mimic the phenotype of alternatively activated (M2) macrophages." (PMID 22272346, 2012).
rheumatoid arthritis (5 papers, 2018 to 2025). A chronic, systemic autoimmune disorder characterized by inflammation in the synovial membranes and articular surfaces. "Carriage of the minor allele of the genetic variant IRAK-3 (rs11541076) has previously been associated with response to TNFi in two studies totaling 1916 patients with rheumatoid arthritis and a study on 118 patients with ankylosing spondylitis or PsA." (PMID 41009564, 2025). "The role of IRAK3 was assessed in rheumatoid arthritis (RA), a disease which is amenable to TNF blockade." (PMID 40370470, 2025). "The other four candidate targets with a link to autoimmunity are DAPK1 (inflammatory bowel disease), MST4 (Grave’s disease), PXK (systemic lupus erythematosus), and IRAK3 (rheumatoid arthritis) (for literature evidence check S1 Table)." (PMID 32459810, 2020).
colorectal cancer (4 papers, 2018 to 2025). A primary or metastatic malignant neoplasm that affects the colon or rectum. "Reduced CD3+FoxP3+ T cells were also observed in the spleens of IRAK3-deficient mice in a colorectal cancer model." (PMID 40370470, 2025).
systemic lupus erythematosus (4 papers, 2017 to 2025). An autoimmune multi-organ disease typically associated with vasculopathy and autoantibody production. "IRAK3 suppresses a murine model of systemic lupus erythematosus (SLE), but a trend towards the association of genetic variants of IRAK3 was not statistically significant in a study of a European SLE population." (PMID 40370470, 2025).
Arthritis (3 papers, 2023 to 2025). Inflammation of a joint. "Using collagen-induced arthritis, a murine model of RA, the immunomodulatory role of IRAK3 was investigated with wild-type (WT) and IRAK3-deficient mice expressing the MHC-II Aq allele." (PMID 40370470, 2025). "Interleukin-1 receptor-associated kinase 3 (IRAK3) has been proven to be overexpressed in arthritis and to perform antagonistically in Toll-like receptor (TLR)-mediated cellular signaling." (PMID 37048045, 2023). "The progression of the disease in IRAK3−/− NQ mice was significantly more rapid, with the average time to arthritis onset being 26 versus 38 days in the WT group." (PMID 40370470, 2025). "We and others have previously demonstrated relatively high levels of inflammatory gene expression (including TNF, which induces IRAK3) in affected joints in arthritis." (PMID 40370470, 2025). "Tnfaip3, Ptpn6 and Irak3 were differentially expressed in affected paws, spleens, lymph nodes and circulating leucocytes in experimental murine arthritis treated with anti-TNF." (PMID 39116634, 2024).